CYCS (cytochrome c, somatic)
Diseases named in the same sentence as CYCS in open-access papers (continued):
Sharing a sentence is not in itself a finding about the gene and the disease.
head and neck squamous cell carcinoma (3 papers, 2022 to 2025). A squamous cell carcinoma that arises from any of the following anatomic sites: lip and oral cavity, nasal cavity, paranasal sinuses, pharynx, larynx, and salivary glands. "In patients with head and neck squamous cell carcinoma (HNSCC), upregulation of CALM1, CYCS, THBS1, MYC, GATA6, and SPRED3 was strongly associated with a poor prognosis." (PMID 36239104, 2022).
metabolic syndrome (3 papers, 2020 to 2024). A cluster of metabolic risk factors for CARDIOVASCULAR DISEASES and TYPE 2 DIABETES MELLITUS. "Some of the DE proteins predicted to affect mitochondrial function also cause dyslipidemia, including MECR, CS, ACLY, AOX3, and COX6B1 by RIS, and CYCS, COX6B1, and ENO3 by OLAN." (PMID 33302598, 2020).
legionellosis (2 papers, 2020 to 2023). Any disease caused by Legionella bacteria. "The results revealed three up-regulated genes (SEC22B, CXCL2, and CYCS) and two down-regulated genes (CA3, CA4) were significantly involved in Legionellosis and nitrogen metabolism pathways, respectively." (PMID 32174961, 2020).
mental disorder (2 papers, 2019 to 2023). A disease that has its basis in the disruption of mental process. "We selected two of these proteins, PPP1R1B and CYCS (cytochrome c somatic), which have been previously associated with psychiatric disorders, including anxiety disorders, for validation by Western blot analysis." (PMID 31557158, 2019).
bipolar disorder (1 paper, 2024). A disorder of the brain that causes unusual shifts in mood, energy, activity levels and the ability to carry out day-to-day tasks. "NDUFV2 was upregulated in bipolar disorder but downregulated in ketosis, whereas CYCS and SDHAF3 were downregulated in bipolar disorder but upregulated in ketosis." (PMID 39125835, 2024).
blood disease (1 paper, 2021). A disease that occurs in the blood. "The top candidates include TNFAIP3, which has been reported before, but also include other, novel regions, containing genes involved in blood diseases (CYCS), neurological diseases (PRKCH, KCNH5, LRNN1), metabolism (SFRP4, SUMF1), and skin development (ASCL4, RAB27A)." (PMID 34032215, 2021).
hypospadias (1 paper, 2020). Hypospadias is the displacement of the urethral meatus on the ventrum of the penis. "Specifically, CYCS was found in lower concentrations (ng/ml) in mild hypospadias (median = 8.86) when compared to control samples (median = 12.56)." (PMID 33425810, 2020). "Given the major role of CYCS as a modulator of apoptosis, we analyzed additional samples by ELISA, which revealed a significant downregulation of CYCS in mild hypospadias as compared to control samples." (PMID 33425810, 2020). "Of note, in this study, CYCS was found significantly downregulated in mild hypospadias samples." (PMID 33425810, 2020).
sarcopenia (1 paper, 2024). Progressive decline in muscle mass due to aging which results in decreased functional capacity of muscles. "Six biomarkers—BTG2, FOXO3, AQP9, GPC3, CYCS, and SCN1B—were identified alongside a diagnostic model that offers a novel approach for early diagnosis of sarcopenia." (PMID 39777262, 2024). "The highlight of our study is the identification of six potential diagnostic markers for sarcopenia: BTG2, FOXO3, AQP9, SCN1B, CYCS, and GPC3." (PMID 39777262, 2024).
vitiligo (1 paper, 2024). Generalized well circumscribed patches of leukoderma that are generally distributed over symmetric body locations and is due to autoimmune destruction of melanocytes. "Cluster12 keratinocyte RBP-expression groups, namely, ZC3H12A, S100A9, CYCS, and EIF5A, were also enriched in the apoptotic pathway in the patients with vitiligo." (PMID 38438962, 2024).
cancer (490 papers, 2002 to 2026). A tumor composed of atypical neoplastic, often pleomorphic cells that invade other tissues. "Then, risk scores were calculated for every cancer sample calculated by using the following formula: Riskraw = DAD1*2.316+CYCS*1.426+CSNK2A2*1.576+VPS25*0.728+VDAC1*0.976+TMLHE*0.381+CYTH3*0.024+PRKCA*0.260-TP73*0.567+FZD6*0.047+SQSTM1*0.094-MAP2K7*3.070." (PMID 35185897, 2022). "Cytochrome C, encoded by CYCS, is a major component of the electron transport chain of mitochondria and it is tightly associated with the pro-survival pathways in normal as well as cancer cells." (PMID 34439877, 2021). "Compared with control cell lines (BEAS-2B), MRPL44 and CYCS were significantly higher expressed in cancer cell lines (A549 and H1299), while CAT was significantly lower expressed." (PMID 36798829, 2023). "Among the studied 17 genes, this is the first report of promoter methylation for CpG sites in H2AX, RNF8 and CYCS in human cancer." (PMID 21092294, 2010). "Upregulation of CYCS has been associated with larger tumor volumes and identified as a negative prognostic marker during cancer treatment." (PMID 40951345, 2025). "Similar to prior research, patients with a low CYCS level show weaker apoptosis of cancer cells." (PMID 35502302, 2022). "CYCS has been reported to be related to breast and colon cancers." (PMID 25333947, 2014). "It was found that apoptosis was induced in cancer cells by increasing BAX levels and decreasing Bcl‐2 levels; CYCS and CASP3 levels, which are ROS‐assisted apoptotic markers, also increased." (PMID 40318008, 2025). "In the collected clinical specimens, qPCR results revealed notably lower CYCS and NFKB1 expression and notably higher IKBKB and TRADD expression in cancer tissues than in healthy paracarcinoma ones (P < 0.05)." (PMID 35502302, 2022). "Importantly, target genes involved in epithelium development (RGMA, SHANK3, PAX6, PFN1, WNT4) and cancer (CBL, CYCS, FGF7, IGF1R, PTEN, PIK3CD, WNT4) address to a further role in the onset of epithelial abnormalities and oncogenesis." (PMID 23936163, 2013). "Although our simulation indicates activation of cytochrome C (CYCS) and thus its release into the cytoplasm in the transition towards cancer (time step 9), there is no induction of apoptosis as evidenced by inactive caspases." (PMID 33578795, 2021).
tumor (375 papers, 1971 to 2026). "CYCS encodes the core component protein of the mitochondrial electron transport chain, which is also involved in the initiation of apoptosis and various tumor processes." (PMID 35185897, 2022). "The CYCS gene encodes cytochrome c, which is closely related to the synthesis of ATP and the survival of tumor cells." (PMID 36277882, 2022). "Cytochrome c somatic (CYCS) is associated with mitochondrial dysfunction and autophagy defects, and it also has potential mechanism in tumor cell proliferation and apoptosis." (PMID 35296025, 2022). "In this study, we explored the role of USP53 as a tumor suppressor in HCC via the deubiquitination of cytochrome c (CYCS), which triggered the mitochondria apoptosis pathway." (PMID 35654790, 2022). "Compared with normal tissues, CASP6, GPX4, NOD2, and WNK1 were upregulated in HCC samples, presenting low- to medium-intensity expressions, and high expression of CYCS emerged in tumor tissues." (PMID 35368686, 2022). "Among them, 6 genes including BCL2, BCL2L11, BAD, CASP7, CASP9, and CYCS expression reduced in tumor tissue compared to normal according to meta-analysis studies and RNA-seq TCGA data." (PMID 33292233, 2020). "Previously, we have reported that the ubiquitin-specific protease (USP) family members USP5 and USP53 act as oncogenes or tumor suppressor genes in HCC via the stabilization of c-Myc and cytochrome c (CYCS), respectively." (PMID 38315284, 2024). "Results showed that the mRNA levels of BNIP3, CYCS, RRAGD, CD44, EIF4E, MAP4K1, and LIN28B were higher in tumor samples, whereas the mRNA levels of PPARGC1A and FLT3 were higher in normal samples." (PMID 38468074, 2024). "It’s found that IHC signals of BNIP3, CYCS, RRAGD, CD44, EIF4E, and MAP4K1 were consistently high in tumor cells of HCC, compared with normal tissues, implying that these genes were indeed ectopically expressed in HCC." (PMID 38468074, 2024). "The peptides with increased presentation in SK-Mel-28 dr cells derived from EIF4B, FAM20B, LDHB, CYCS, C5orf22, RCAN1 and DIEXF and were recurrently identified in TvHdb in a variety of tumor patients." (PMID 39835134, 2024). "In addition, CYCS and NFKB1 presented low expression, while IKBKB and TRADD presented high expression in TCGA and clinical tumor samples." (PMID 35502302, 2022). "Finally, we used TIMER database determine the correlations between GALNT3, CYCS, EIF5A, and ITGB4 and six types of tumor-infiltrating immune cells." (PMID 35651789, 2022). "Despite the hypomethylation state of DR4 receptor and hypermethylation state of anti-apoptotic decoy receptors (DCR1 and DCR2), we propose that the final outcome in tumor pathogenesis depends on downstream signal transduction molecules, such as CASP8, FLIP and CYCS in established tumors." (PMID 21092294, 2010). "Moreover, DK1 also enhanced the expression of several other tumor suppressor genes that are related to this pathway such as FOXO, TP73, CDKN1A, Caspase, CYCS, and GADD45A while impeded the expression of other proto-oncogenes namely PIK3R3, BCL-2, IGFBP2, HGF, and FGF." (PMID 34204873, 2021). "Another interesting finding in our results is that the four prognostic PRGs (BAK1, CYCS, HMGB1, and NLRP1) were significantly correlated with immune cell infiltration, which further confirmed that pyroptosis in immune cells might participate in regulating the tumour microenvironment." (PMID 37337018, 2023).
infection (111 papers, 2007 to 2026). The state of being infected such as from the introduction of a foreign agent such as serum, vaccine, antigenic substance or organism. "For instance, measles virus vaccine strain Edmonston B (MV-Edm) infection activates mitophagy, leading to a decrease in the release of somatic cytochrome C (CYCS)." (PMID 37650304, 2023). "Three key proteins, including FLNA, TXN, and CYCS, were subjected to Western blot analysis at 0, 4, and 24 h post infection (hpi) to validate the iTRAQ process." (PMID 37264422, 2023). "Edmonston B (MV-Edm) infection induced mitophagy and reduced the release of cytochrome c (CYCS) to the cytoplasm and thus blocked the pro-apoptotic cascade, thereby maintaining MeV replication in non-small lung cancer cell." (PMID 36590405, 2022). "Another gene PNPT1, which was documented recently to be released from mitochondria coordinately with CYCS and to possess a new pro-apoptotic role, was similarly increased in line 72 spleen samples after infection." (PMID 31252692, 2019). "However, overexpression of CYCS in HuR cKO mice by infection with an AAV that expressed CYCS did not rescue the effect of HuR deletion in aggravating HFD-induced NAFLD." (PMID 32546794, 2020).
neurodegenerative disease (19 papers, 2015 to 2026). A disorder of the central nervous system characterized by gradual and progressive loss of neural tissue and neurologic function. "The prevalent pathways that were differentially affected during male ageing relate to neurodegenerative diseases such as HD, AD, and PD; in this case, the implicated genes (CASP7, CALM3, CYCS, SDHC, multiple subunits of Complex I, Complex IV, and ATP synthase) are downregulated." (PMID 25977747, 2015).
mitochondrial disease (5 papers, 2016 to 2026). "A combined urinary biomarker panel—including stress markers (GDF15, CYCS, and PRDX2), immune effectors (MPO and C4A), ECM proteins (COL1A1 and CCN2), and selected amino acids—could support diagnosis, patient stratification, and longitudinal monitoring in mitochondrial disease." (PMID 41373442, 2025).
CYCS also shares sentences with these, for which no sentence is quoted: leukemia (55 papers); ischemia (50); neuroblastoma (43); glioma (39); pancreatic cancer (31); Cerebral ischemia (30); liver cancer (27); Parkinson disease (24); Hyperglycemia (19); Stroke (19); osteosarcoma (15); COVID-19 (13); multiple myeloma (11); oral cancer (11); bladder cancer (10); myocardial ischemia (10); non-small cell lung carcinoma (10); Obesity (10); myocardial infarction (9); heart failure (8); ischemic stroke (8); promyelocytic leukemia (8); thyroid cancer (8); acute myeloid leukemia (7); asthma (7); cardiac arrest (7); diabetic retinopathy (7); Hypertension (7); acute lymphoblastic leukemia (6); colitis (6).
A further 259 diseases each share a sentence with CYCS in 6 papers or fewer.